BRAF (B-Raf proto-oncogene, serine/threonine kinase)
Diseases named in the same sentence as BRAF in open-access papers (continued):
Sharing a sentence is not in itself a finding about the gene and the disease.
cancer (continued). "SHP2 is a critical regulator of RAS MAPK pathway and SHP2 inhibitors have activity in cancers with KRAS mutations and BRAF mutations." (PMID 32516941, 2020). "Although the number of cancer somatic mutations has been increasing at a fascinating speed, our knowledge of distinguishing driver mutations from passenger mutations remains limited, even in best-studied cancer genes such as EGFR and BRAF." (PMID 32079540, 2020). "Two MEK inhibitors (trametinib and cobimetinib) have been developed and approved for treating BRAF(V600E)-harboring cancers as single agents or together with RAF inhibitors, while ERK inhibitors are still undergoing clinical trials." (PMID 31941155, 2020). "The BRAF gene ranked first by the number of PTM-related mutations in SKCM and harbored multiple significant PTM mutations in several cancer types." (PMID 33240890, 2020). "Mutations in the B-Raf proto-oncogene (BRAF) generate activation of the mitogen-activated protein kinase (MAPK) signaling pathway and increase growth and proliferation of cancer cells." (PMID 32992737, 2020). "BRAF gene testing had reached the bedside from the bench-side in the wind of cancer precision medicine." (PMID 33152998, 2020). "The BRAF p.Val600Glu (V600E) cfDNA from cancer patients was shorter compared with the corresponding BRAF WT cfDNA from the same patients or from the healthy controls, with additional local maxima at around 134–144 bp but retaining the peak at 166 bp." (PMID 32650715, 2020). "Several research studies on the resistance mechanism of BRAF targeting therapy have demonstrated the importance of a profound understanding of the RAS–RAF–MEK–MAPK pathway in conquering this malignant tumor." (PMID 33152998, 2020). "Approximately 45–50% of BRAF mutant cancers demonstrate dysregulated WNT signaling, and thus the WNT signaling pathway appears to be important to serrated colorectal neoplasia." (PMID 32384699, 2020). "We also introduce recent developments in cancer precision medicine, which would serve as a tailwind for the widespread adoption of BRAF genetic testing." (PMID 33152998, 2020). "Two selective BRAF inhibitors, vemurafenib and dabrafenib, have been approved by the United States Food and Drug Administration for the treatment of BRAF V600-positive cancer." (PMID 32714388, 2020). "Nocodazole appears, however, to be less tubulin specific as it has been reported to be a high affinity ligand for cancer-related kinases including Abl, cKit, BRAF, and MEK." (PMID 32425788, 2020). "In this study, we analyzed a large number of 10,000 patients with advanced cancers for oncogenic mutations in EGFR, ERBB2, BRAF, and MAP2K1, especially for those located within the kinase domain β3‐αC loop." (PMID 32757330, 2020). "As with the continued clinical development of BRAF inhibition in BRAF mutant cancers, the activity of PLX8394 should be investigated as part of a combination with other drugs that limit pathway reactivation such as MEK and EGFR inhibitors." (PMID 32922659, 2020). "Cancer type and BRAF/MAPK inhibitor use status exhibited different distributions between males and females." (PMID 33203961, 2020). "This BRAF mutation activates signaling of the MAPK pathway, and promotes cancer cell proliferation and immune escape." (PMID 32260561, 2020). "KRAS (Kristen Rat sarcoma), one of the RAS isoforms, plays an important role in human cancers acting upstream of BRAF." (PMID 32637031, 2020). "This upregulation requires ERK activity and inhibition of p38 and was also observed in other cancer cells carrying KRAS, BRAF, or NF1 mutations, suggesting that p38 antagonizes this resistance pathway in several different cancer types." (PMID 32046099, 2020).
cancer (continued). "In contrast, the examination of potential IDH1 alterations in 161 MSS CRCs revealed four cancers with IDH1 mutation, which were all CIMP-positive and BRAF mutant." (PMID 32610612, 2020). "For example, drugs that target kinase activation in BRAF‐mutant cancers depend on structural variations in the BRAF kinase domain." (PMID 32757330, 2020). "The repression of these cancer hallmarks reflects blockage of the key oncogenic signaling pathway upon initial BRAF inhibition." (PMID 32393797, 2020). "These cancers have higher frequency of KRAS and BRAF mutations compared with conventional cancers, correlating to shorter overall survival." (PMID 32545410, 2020). "Considering that some mutations such as KRAS G12D and BRAF V600E are selectively enriched during cancer development, which could skew our estimation of mutation tendency, we excluded mutational events that occur in more than five cancer samples (see “Methods” for further discussion)." (PMID 32704382, 2020). "This is a unique finding for FGFR1 and RGNT, as there is not typically selection pressure for loss of the remaining wildtype allele for other mutated oncogenes in human cancers of any other type (e.g. KRAS, BRAF, EGFR)." (PMID 32859279, 2020). "Selumetinib is a potent, highly selective MEK1/2 inhibitor with an inhibitory effect in various cancer types, especially in BRAF and/or RAS mutant tumors." (PMID 33081092, 2020). "Further studies have identified a clear relationship between the presence of the mutant BRAF V600E protein and elevated glycolytic activity in various cancers." (PMID 32046099, 2020). "To further characterize the differentiation state of BRAF FOXE1+/+ and BRAF FOXE1+/− cancers, we analyzed the expression of a panel of thyroid differentiation markers by quantitative RT-PCR." (PMID 33375029, 2020). "Our objective is to design and evaluate hybridization properties of multiple model helices containing three cancer-related probes, BRAF, KRAS, and EGFR, bound to complementary and mismatched RNA." (PMID 36703315, 2020). "This generates a dependence on MCL-1 in treated cancer cells, that can be therapeutically overcome by sequential inhibition of BRAF and MCL-1 in preclinical studies." (PMID 32722518, 2020). "The sensitivity of cancer cells to drugs can often be compromised by PIK3CA, Ras and BRAF mutations." (PMID 33371382, 2020). "We further revealed that the combination of MEK2 inhibition by lycorine and BRAF inhibition by vemurafenib resulted in enhanced anti-cancer activity in CRC, providing evidence of the potential of targeted combination regimens for personalized therapy." (PMID 31901897, 2020). "Several targeted inhibitors against BRAF mutations or other key components of MAPK pathway are emerging, but unfortunately, differently from other cancers, BRAFmt mCRCs resistance to single targeted-drug regimens is broadly attested in clinical practice." (PMID 32015690, 2020). "Drug-promoted cancers are increasingly recognized as a serious clinical problem in patients receiving BRAF inhibitory treatment." (PMID 33042833, 2020). "Ponatinib inhibited ERK signaling activity in cancer cells driven by either BRAF monomers or dimers." (PMID 32873792, 2020). "The activation mutation of serine threonine kinase v-RAF mouse sarcoma virus oncogene B1 (BRAF) is an important biomarker in human benign and malignant tumors, and most mutations affect BRAFV600 in exon 15 of BRAF gene." (PMID 32477264, 2020). "Collectively, these data indicate that the mutation of both BRAF and APC results in an aggressive and rapidly progressing cancer phenotype and confers a poor prognosis." (PMID 32384699, 2020). "One-third of human tumors are driven by RAS mutations, especially the KRAS isoform, whereas approximately 8% of tumors express an activated form of BRAF, accounting together for almost 40% of cancers." (PMID 32858836, 2020).
cancer (continued). "Specifically, BRAF FOXE1+/+ thyroid tissue displays a dramatic loss of the normal follicular structure, featuring a solid growth pattern as expected for this cancer model, while BRAF FOXE1+/− glands show empty structures, resembling residual follicle lumens." (PMID 33375029, 2020). "Blood samples were obtained from cancer patients with defined driver gene hotspot mutations, including EGFR-T790M (n = 32), EGFR-L858R (n = 28), BRAF-V600E (n = 13), PI3KCA-E545K (n = 13), KRAS-G12C (n = 13), and KRAS-G12V (n = 6)." (PMID 32180799, 2020). "Hyperactive MAPK signaling is responsible for a large portion of cancers, and genetic alterations that aberrantly activate this pathway mainly occur on receptor tyrosine kinases (RTKs), Ras small GTPases, and BRAF." (PMID 32807225, 2020). "Mitochondrial fission driven by activating phosphorylation of DRP1 (pDRP1S616) downstream of both KRAS or BRAF pathway/s confers a growth advantage as well as metabolic shift towards a more glycolytic phenotype in various models of cancer." (PMID 33738242, 2020). "CRISPR screens of genome and customized sgRNA libraries in numerous disease models have identified novel oncogenic drivers and cancer dependencies, synthetic lethal interactions with mutant RAS and BRAF and mechanisms of resistance to anti-cancer drugs." (PMID 33072611, 2020). "The inhibition of the BRAFV600E gene mutation through BRAF and MEK-inhibitors is an established treatment in a variety of cancers including melanoma, thyroid cancer and non-small cell lung cancer (NSCLC)." (PMID 32932925, 2020). "In conclusion, based on a large cohort of cancer patients, our study analyzed mutations in β3‐αC loop in kinase domain of EGFR, ERBB2, MAP2K1, and BRAF, and summarized the drug‐relevant mutations of each gene." (PMID 32757330, 2020). "We next evaluated the relationship between BRAF mutation and APC mutation in further detail, to characterize the clinical and molecular correlates of this subtype of cancers." (PMID 32384699, 2020). "By sheltering cancer cells from BRAF inhibition, this study revealed that CAFs provide a safe haven favoring the formation of resistant clones." (PMID 33291749, 2020). "There are still many areas open to further research, including investigations on anti-cancer effect by combination with other inhibitors to targets of Ras-signal cascade such as BRAF and MEK." (PMID 33303890, 2020). "Kirsten rat sarcoma viral oncogene homolog (K-Ras) is an upstream regulator of BRAF and the mutant KRAS is associated with aggressive cancer phenotypes and poor patient prognosis." (PMID 33299639, 2020). "Mutant BRAF has been involved in the pathogenesis of many cancers but can also be seen in benign conditions." (PMID 32384640, 2020). "As we demonstrated in this study, BRAF V600E and Src are part of the multi-driver mechanism in the HT-29 cancer cell line." (PMID 32069833, 2020). "A recent study has revealed that MYC alterations are mutually exclusive with PIK3CA, PTEN, APC, or BRAF alterations, suggesting MYC amplification as a distinct driver mutation in the cancer genome." (PMID 32235890, 2020). "Several studies reported that MSS CRCs, associated with BRAF mutations, show higher mortality and decreased overall survival with respect to both MSI/BRAF mutated and MSS/KRAS mutated cancers." (PMID 31330830, 2019).
cancer (continued). "Oncogenic activation mutations in upstream kinases BRAF, MEK, EGFR and HER2 are frequently observed in cancer." (PMID 31407663, 2019). "In BRAF-mutant cancers, these “stem-like” cells can tolerate otherwise toxic levels of MAPK perturbation by activating a cellular de-differentiation program through epigenetic modifications." (PMID 31426419, 2019). "In this Review, we discuss the role of epigenetic mechanisms and phenotype plasticity in determining the outcome of MAPK pathway-targeted therapies in BRAF-mutant cancers." (PMID 31581557, 2019). "Molecularly, BRAF mutant/MSS cancers have multiple genetic aberrations that are representative of typical changes associated with both serrated and conventional pathways." (PMID 31455041, 2019). "Thus, preventing RAF dimerization is an effective strategy for the development of inhibitors with improved safety and durable efficacy and could provide clinical benefits to patients with cancer driven by not only BRAF mutations but also RAS mutations on the BRAF-wildtype background." (PMID 30679688, 2019). "The cmDNA fraction was informative in all 19 RAS/BRAF wild type patients, therefore bypassing the need to extensively sequence cancer tissue and design individualized assays in this subpopulation." (PMID 31355139, 2019). "For the first time, with this work, we suggest that BRAF mutant/MSS cancers include the rare entity of CRbCs, characterized by a strong activation of EMT and complete loss or reduced expression of SMARCB1 (INI-1)." (PMID 31455041, 2019). "Altogether, these data demonstrated distinct clonal compositions in BRAF-driven tumors across cancer types and the propensity for more linear evolutionary trajectories in BRAFV600E-driven SKCM tumors." (PMID 31723142, 2019). "In our effort to survey the prevalence of BRAF mutations in Chinese NSCLC patients, we have conducted a multi-center retrospective study involving 5 cancer centers." (PMID 31470866, 2019). "Considering cancers with a high MSI status, the association between PTEN and BRAF mutations remained significant (p = 0.019)." (PMID 31717544, 2019). "For that reason, BRAF inhibitors have been extensively studied, showing promising results against various cancer types, especially melanoma." (PMID 35582564, 2019). "In contrast, more immunogenic cancer cells with endogenous JAK2 deletion and BRAF or KRAS mutation (RKO and HCT116) displayed tolerance to momelotinib, reducing the combinatory effect." (PMID 30670049, 2019). "Most of the molecular-targeted drugs used in the treatment of NSCLC inhibit specific targets that induce cancer evolution [so-called “oncogenic drivers (i.e., EGFR mutation, ALK translocation, ROS1 translocation, and BRAF mutation)”]." (PMID 31049758, 2019). "A better understanding of BRAF biology and an improved classification of the BRAF gene alteration spectrum in cancer enabled the identification and design of small molecule inhibitors that specifically inactivate the catalytic activity of BRAF." (PMID 31426419, 2019). "Prior to the identification of BRAF mutations, the first-generation ATP-competitive RAF inhibitor, sorafenib (Nexavar), was developed for targeting RAS-mutant cancers." (PMID 31581557, 2019). "These decreases were observed in both BRAF- and NRAS-mutated arms, and were moderate and consistent with observations in other cancer studies with MEK inhibitors, such as the observed suppression of pERK by cobimetinib (GDC-0973) both in vitro and in vivo." (PMID 30956763, 2019). "This recently identified inhibition of chemokine secretion by PLX4720 (and potentially by other BRAF inhibitors) implies that our knowledge on the anti-cancer effects in cancer of these drugs is still incomplete." (PMID 31762942, 2019). "Studies of RAF inhibitors in cancer led to the discovery of complex compensatory interactions between BRAF and RAF1 that drive a paradoxical increase in ERK1/2 activation." (PMID 31017896, 2019).
cancer (continued). "Consistent with reduced TET activity, global levels of 5hmC were lower in the BRAFV600E than in BRAF wild-type cancer cells or normal colon epithelial cells." (PMID 31842975, 2019). "The signaling protein BRAF is a carcinogenic factor, which is phosphorylated and mutated to cause expression to maintain its activity to activate target gene MAPK1 to induce cancer cells’ proliferation, migration and cell cycle." (PMID 31126066, 2019). "Because cancer, particularly solid tumors, is a heterogeneous disease involving disparate aberrant mutations, such as KRAS and BRAF mutations, predicting clinical outcome from a few mutations is difficult." (PMID 31208461, 2019). "In the case of PTC, it is accepted that it is a MAPK pathway-driven cancer with RAS and BRAF activating mutations being the main oncogenic players, which are found in an exclusive manner." (PMID 31312183, 2019). "Intense research efforts regarding cancer genomes have identified several oncogenic pathways important in human cancers, and have led to improved therapeutic outcomes for tumors with EGFR, ALK, and BRAF mutations." (PMID 31848373, 2019). "The BRAF V600E mutation, by activating the MAPK cascade, stimulates the production of a wide spectrum of chemokines by cancer cells." (PMID 31762942, 2019). "Unfortunately, in the present study from cancer registry-based population recorded between 2004 and 2009, mutational analysis of RAS and BRAF genes were performed only in a minority of cases insufficient for statistical analysis." (PMID 30842570, 2019). "Here, we show that endothelial cell‐restricted ablation of BRAF, a kinase frequently activated in cancer, prevents vascular leaking as well metastatic spread." (PMID 30828992, 2019). "citrata Kenting Water Mint which can be potentially used in preventing BRAF inhibitor drug-induced cutaneous side-effects in cancer patients." (PMID 31242703, 2019). "Only a small number of genes have alterations that are specifically listed in a US Food and Drug Administration–approved indication that would match a patient with cancer to a specific actionable agent—for example, BRAF V600E to vemurafenib." (PMID 32914008, 2019). "Reverse Phase Proteomic Array (RPPA, MD Anderson Cell Lines Project), RNAseq (Cancer Cell Line Encyclopedia) and vemurafenib sensitivity (Cancer Therapeutic Response Portal) data for BRAF-V600E cancer cell lines were curated." (PMID 31672130, 2019). "BRAF is a common oncogene in many cancers, conferring constitutive activation of proliferation pathways." (PMID 35582564, 2019). "Molecular subtyping is a cornerstone of precision medicine in cancer treatment, and the mutation status of genes in the EGFR pathways, including RAS genes, PIK3CA, PTEN and BRAF have been shown to predict response to EGFR blockade therapy in CRC." (PMID 31775679, 2019). "Altogether, these alterations highlight the reliance of multiple cancer subtypes on oncogenic BRAF-MEK-ERK signaling, implicating the BRAF kinase as an exploitable vulnerability and a therapeutic target for such cancers." (PMID 31581557, 2019). "We discuss the predominant BRAF mutations and we outline therapeutic strategies to block mutant BRAF and cancer growth." (PMID 31426419, 2019). "A greater percentage of BRAF V600EE patients were diagnosed at a higher stage of cancer, suggesting a faster and more aggressive growth pattern compared to the mutation negative patients, and the higher stage accounted reflected in higher death rate." (PMID 31810221, 2019). "As expected, known cancer proteins BRAF, PIK3CA, KRas, Akt1, IDH1, and NRas showed the highest hotspot mutation scores in the TCGA dataset." (PMID 31345222, 2019).